LINC01637 (long independently transcribed non-coding RNA 1637)
Gene: Long non-coding RNA gene on chromosome 22 (20,957,092 to 20,964,881, forward strand). Ensembl gene ENSG00000237476.
Diseases named in the same sentence as LINC01637 in open-access papers:
LINC01637 is named in the same sentence as 3 diseases in open-access papers, as found by Europe PMC text mining. Sharing a sentence is not in itself a finding about the gene and the disease.
LINC01637 shares sentences with these, for which no sentence is quoted: pancreatic adenocarcinoma (1 paper); tumor (1); uveal melanoma (1).